TLR4 (toll like receptor 4)
Diseases named in the same sentence as TLR4 in open-access papers (continued):
Sharing a sentence is not in itself a finding about the gene and the disease.
aneurysm (17 papers, 2013 to 2026). Bulging or ballooning in an area of an artery secondary to arterial wall weakening. "It has been found that MyD88 knockout and targeted knockout of TLR4-encoding genes in hypercholesterolemia mouse models can both inhibit the formation of aneurysms." (PMID 38284891, 2024). "The experimental data show that TLR4 expression reached its peak 1 month after aneurysm induction and decreased to the level before aneurysm induction 3 months after." (PMID 38137108, 2023). "TLR4 remains a highly feasible actor in both the mechanism of aneurysm development and an immunological cascade of SAH." (PMID 34200256, 2021). "PPAR alpha promotes formation and rupture of aneurysms in mice, but also decreases vasospasm-related cytokines and hemoglobin-induced TLR4 expression in vascular myocytes." (PMID 31595394, 2020). "In present study, we demonstrate a potential mechanism that TLR4 is an integral signaling molecule in regulating not only proteinase expression but also inflammation in VSMCs during aneurysm formation." (PMID 26741694, 2016). "TLR4 expression is apparently upregulated in the endothelial cell layer and adventitia of aneurysm walls, and increases MMP9 expression in macrophages, which promote aneurysmal formation." (PMID 23844137, 2013). "Taken together, higher MLDGS score may represent higher expression of IL1B, TLR4, VEGFA and MMP2, and lower expression of NOS3, implying inferior vascular stability at the molecular level and high risk of aneurysm rupture and CVS onset." (PMID 36844725, 2023). "TLR4 is located on chromosome 9q32-q33 and has been believed to link inflammation to aneurysms." (PMID 30530865, 2019). "In addition, S100A12, another DAMP molecule recently recognized as a common ligand of RAGE and TLR4, has been associated with production of IL-6 and MMP-2 and enhancement of aneurysm formation." (PMID 26741694, 2016). "Despite these findings, the mechanism by which TLR4 might positively regulate aneurysm formation remains mostly unclear." (PMID 26741694, 2016). "Herein we aimed to obtain further insight into the mechanism by which TLR4 might promote aneurysm formation." (PMID 26741694, 2016). "In summary, the results obtained from human samples and different mouse models suggest that upregulation of TLR4 in VSMCs may contribute to AAA formation since aneurysm initiation and corroborate the critical role for TLR4 signaling in AAA." (PMID 26741694, 2016). "In summary, although the TNF-α level and macrophage number were similar in ScSnJ and ScNJ mice during aneurysm initiation, knockout of TLR4 signaling reduced IL-6 and MCP-1 levels, suppressed HMGB1 and RAGE expression and interfered with consequent accumulation of macrophages." (PMID 26741694, 2016). "In AAA, toll-like receptor 4 (TLR4) expression is upregulated, and its activation promotes MyD88-dependent inflammatory signaling that accelerates aneurysm progression." (PMID 41484507, 2026). "Regarding this, a positive correlation between TLR4, MMP9, and MMP2 and aneurysm development has been reported." (PMID 37445606, 2023). "Taken together, these findings revealed that knockout of TLR4 ameliorated vascular inflammation preceding AAA formation, thereby protecting mice from aneurysm development." (PMID 26741694, 2016). "However, based on our results it can be assumed that TLR4 and TLR9 respond not only to blood degradation products but also to increased ICP following aneurysm rupture and extravasation of blood into the subarachnoid space." (PMID 39839349, 2024). "TLR4/MyD88 KO mice had a reduction in aneurysm rupture rates but not in incidence of aneurysm formation." (PMID 36293468, 2022). "Moreover, rosiglitazone also plays a potential protective role in the formation and rupture of aneurysms through the inhibitory effect on c-Jun N-terminal kinase (JNK) phosphorylation and toll-like receptor 4 (TLR4) expression at the site of lesion formation." (PMID 36589814, 2022).
aneurysm (continued). "TLR4 signaling mediates proteinase release from VSMCs, and more important, contributes to AAA formation by promoting cytokine production, specifically IL-6 and MCP-1, during aneurysm initiation and development." (PMID 26741694, 2016). "Therefore, targeting TLR4 may serve as a potential therapeutic strategy for AAA, especially in the early stage of aneurysm formation." (PMID 26741694, 2016).
chorioamnionitis (17 papers, 2006 to 2025). A morphologic finding indicating inflammation of the fetal sac membranes. "TLR-4 is highly expressed in preterm human placentas from complicated chorioamnionitis and has been extensively associated with PTD." (PMID 23762418, 2013). "We assessed the eNAMPT/TLR4 inflammatory pathway as a druggable IAI target in pregnancy utilizing a humanized eNAMPT-neutralizing mAb in a murine model of IAI/chorioamnionitis-induced uterine and neonatal inflammation as well as premature birth." (PMID 37415908, 2023). "Intraamniotic inflammation resulting from E. coli invasion was assessed with IHC for inflammatory markers (TLR-4, P-NF-κB) and neutrophil marker (Ly-6G) for chorioamnionitis at 6- and 24-h post-inoculation." (PMID 34855804, 2021). "These divergent results from cell culture and ex-vivo experiments were probably a result of the considerable heterogeneity of human chorioamnionitis when compared to the TLR4-targeted effect of LPS." (PMID 32916274, 2020). "In fact, Hofbauer cells from women with chorioamnionitis overexpress TLR4, possibly to amplify the inflammatory signals that restrain bacterial infections." (PMID 31357391, 2019). "At early GA, low intestinal TLR-4 and MD-2 mRNA levels were detected which were further down regulated during endotoxin-induced chorioamnionitis." (PMID 19503810, 2009). "The purpose of our study was to determine if the fetal skin develops an inflammatory response (dermatitis) and evaluate whether the expression of TLR-2 and TLR-4 is altered in cases of histological chorioamnionitis." (PMID 17064297, 2006). "Given that TLR2 and TLR4 provide an innate immune response against gram-positive and gram-negative bacteria, one might assume that CB monocytes are capable of mounting particularly potent pro-inflammatory responses against pathogens frequently involved in chorioamnionitis and neonatal sepsis." (PMID 36902350, 2023). "In chorioamnionitis, which leads to PTB, LPS-induced translocation of TLR4 toward the basal membrane is a protective mechanism to lower the immune response." (PMID 32508811, 2020). "During chorioamnionitis, the normal polarized distribution pattern of TLRs is completely lost, resulting in the overall upregulation of TLR2 and TLR4 expression." (PMID 32508811, 2020). "This TLR4 expression, together with TLR2, is induced by chorioamnionitis." (PMID 31357391, 2019). "Expression of TLR4 has also been reported in preterm and term placentae of normal women and those with chorioamnionitis and in myometrium and decidua." (PMID 26157394, 2015). "TLR4 immunoreactivity is increased in placentae of preterm cases with chorioamnionitis compared with those of preterm or term placentae without chorioamnionitis." (PMID 26157394, 2015). "Spontaneous labor at term and preterm delivery with histologic chorioamnionitis, regardless of the membrane status (intact or ruptured), is associated with an increased expression of TLR-2 and TLR-4 in the fetal membranes." (PMID 22899878, 2012). "The fetal skin expressed TLR-2 and TLR-4 in the epidermis regardless of histological chorioamnionitis status." (PMID 17064297, 2006). "Our preclinical studies suggest that the attenuation of eNAMPT/TLR4 inflammatory signaling is a potentially novel therapeutic strategy to reduce maternal and fetal/neonatal morbidities and mortalities as well as prematurity in human pregnancies complicated by IAI/chorioamnionitis." (PMID 37415908, 2023). "Furthermore, histologicalpresence of chorioamnionitis did not alter TLR4expression while the progression of gestation significantly decreased the TLR4 expression." (PMID 24520479, 2013). "However, immunoreactivity of TLR-4 in the fetal skin was constitutively expressed, regardless of the presence or absence of chorioamnionitis." (PMID 17064297, 2006). "TLR-4 immunoreactivity in the keratinocytes was constitutive and diffuse throughout the whole layer of epidermis regardless of whether or not histological chorioamnionitis was present." (PMID 17064297, 2006).
chorioamnionitis (continued). "At the maternal–fetal interface, chorioamnionitis activates innate immune pathways in the placenta and membranes via TLR2/TLR4 recognition of Gram-positive or Gram-negative pathogen-associated molecular patterns (PAMPs), triggering the MyD88–NF-κB signaling cascade." (PMID 41102816, 2025).
diabetic neuropathy (17 papers, 2013 to 2025). A chronic, pathological complication associated with diabetes mellitus, where nerve damages are incurred due to diabetic microvascular injury involving small blood vessels that supply these nerves, resulting in peripheral and/or autonomic nerve dysfunction. "Further, the Notch signalling pathway has been studied in diabetic retinopathy, and crosstalk between the Notch-1 and TLR4 signalling pathways has been reported to be one of the key mechanisms in the development and/or progression of diabetic neuropathy." (PMID 35291879, 2022). "In this study, we found the interaction between GABAB receptors and TLR4/Myd88/NF-κB pathwaysin the spinal cord in diabetes neuropathy." (PMID 30647535, 2018). "Since TLR4 is widely distributed in the nervous system and also has an important role in the regulation of neuroinflammation, the unique role of TLR4 in diabetic neuropathy should be further clarified." (PMID 29097792, 2017). "Intrathecal injection of either Notch1 inhibitor DAPT or TLR4 inhibitor TAK ameliorated diabetic neuropathic pain behaviors, which implied that inhibition of either Notch1 signaling or TLR4 signaling alleviated painful diabetic neuropathy." (PMID 29097792, 2017). "In this study, the pain behaviors developed in the painful diabetic neuropathy model were reversed by either Notch1 inhibitor DAPT or TLR4 inhibitor TAK, suggested that different pathways were involved." (PMID 29097792, 2017). "In the present study, both DAPT and TAK were used as the specific inhibitors for detecting the interactions of Notch1 and TLR4 in the progression of diabetic neuropathy." (PMID 29097792, 2017). "The fact that Notch signaling pathway is crucial for neuronal differentiation and survival suggested that interactions between TLR4 with members of Notch1 signaling regulate certain aspects of latency of the neurons affected diabetic neuropathy." (PMID 29097792, 2017). "In a study, apigenin ameliorated diabetic neuropathy in rats by modulating the TLR4/MyD88 signalling pathway, which showed inhibited elevated plasma glucose levels, TNF-α, ILs, TLR4, and MyD88 expressions, thus ameliorating STZ (Streptozotocin) -induced allodynia and hyperalgesia." (PMID 40205269, 2025). "In addition, our findings are limited to a cellular model; further in vivo experiments are required to fully establish the significance of TLR4 signalling in the aetiology of diabetic neuropathy." (PMID 38525707, 2024). "Given that oxLDL and saturated fatty acids derived from LDL and triglycerides can act as ligands for TLR4, lipid abnormalities may be involved in the early onset and development of diabetic neuropathy via the TLR4 pathway." (PMID 38525707, 2024). "Interestingly, interactions of Notch1 and TLR4 signaling pathway play an essential role in DRG of the diabetic neuropathy model because inhibition of one pathway could affect the activation of the other." (PMID 29097792, 2017). "TLR4 and Notch signaling may be crucial in the progression of painful diabetic neuropathy." (PMID 29097792, 2017). "As a proinflammatory mediator, HMGB1 is involved in diabetic neuropathy by binding with RAGE and TLR4 and regulating autophagy." (PMID 37065747, 2023). "subjected KKAy mice to intermittent hypoxia to establish a diabetic neuropathy model and found that the protein expression levels of HMGB1 and TLR4 were increased and neuronal apoptosis was exacerbated." (PMID 37065747, 2023). "Collectively, these findings suggest the interaction between TLR4/MyD88/NF-κB signaling pathways and CXCR4 plays an important role in the diabetic neuropathy." (PMID 30647535, 2018). "PCR and Western blot analysis revealed time-dependent upregulation of TLR4 mRNA and protein, Notch1 mRNA, NICD1 protein, which was paralleled by pain behavior of the established diabetic neuropathy." (PMID 29097792, 2017).
diabetic neuropathy (continued). "In addition, another HMGB1‐specific inhibitor, glycyrrhizin reverses the upregulation of HMGB1 and its receptors (TLR4 and CXCR4) in mice with diabetic neuropathy, improving mechanical and thermal pain threshold in these animals." (PMID 35706377, 2022). "The aim of the current work was to uncover the anti-allodynic and neuroprotective effects of memantine in a model of mouse diabetic neuropathy and its ameliorative effect on the high-mobility group box-1 (HMGB1)/toll-like receptor 4 (TLR4)/nuclear factor-k B (NF-kB) inflammatory axis." (PMID 33915770, 2021). "However, the roles of TLR4 and oxLDL in the pathogenesis of diabetic neuropathy are not fully elucidated." (PMID 38525707, 2024). "Several biomarkers have been suggested, as neuron-specific enolase, toll-like receptor 4 or tumor necrosis factor alpha (TNF-α), but they are not specific of diabetic neuropathy." (PMID 32092076, 2020).
infarction (17 papers, 2009 to 2025). A localised pathological necrosis of tissue resulting from obstruction of the blood supply usually by a thrombus, an embolus, or vascular torsion. "Pretreatment with Nicorandil improved cardiac functions, infarction, and inflammation by inhibiting TLR4/MyD88/NF‐κB/NLRP3 signalling pathway thus reduced myocardial pyroptosis in rats with AMI." (PMID 39929748, 2025). "A number of studies noted increased gut and brain permeability post-infarction through increases in TLR4 expression or reduced expression of tight junction proteins (occludin and ZO-1)." (PMID 40485663, 2025). "M2‐Exosome promoted miR‐148a expression thus ameliorated myocardial pyroptosis, cardiac injuries, myocardial Ca2+ overload and infarction through TXNIP/TLR4/MyD88/NF‐κB/NLRP3 signalling pathway in I/R rats." (PMID 39929748, 2025). "TLR2 and TLR4 agonists trigger platelet activation in patients with AMI through NF-kappa B. Previous studies showed that the activation of TLR2 and TLR4 induced the innate immune response, increasing infarction size and influencing ventricular remodeling." (PMID 35463752, 2022). "Amount of literature show that suppression of TLR4/NF-κB pathway attenuates brain edema and infarction volume and enhances antiapoptotic ability in MCAo model of rats." (PMID 34257822, 2021). "In animal studies, stimulation or inhibition of TLR2 and TLR4 resulted in corresponding changes in pro-inflammatory cytokines, brain infarct volume, and functional outcomes." (PMID 31159847, 2019). "It is demonstrated here that the inhibition of TLR4 expression attenuated cardiac inflammation, reduced infarct size and improved heart function after infarction." (PMID 26290459, 2015). "Taking the TLR2/TLR4/NF-κB pathway as the entry point, we found that the mRNA and protein expression of TLR2, TLR4, and NF-κB were progressively upregulated with the prolongation of infarction time, and a significant difference was observed in the 12 h compared with the Sham group (⁣∗∗p < 0.01)." (PMID 40520774, 2025). "Both TLR4 and MyD88 may contribute to myocardial inflammation and infarction after I/R via NF-κB activity." (PMID 39065537, 2024). "The higher expression of NF-κB and TLR-4 in our study was in agreement with previous reports that TLR-4 receptors have cytotoxic roles in ischemic brain injury, and TLR-4 knockdown is linked to reduced infarction area." (PMID 31293416, 2019). "The TLR2/TLR4/NF-κB pathway exhibited a pronounced activation in the hyperacute phase of AIS, with a discernible correlation between its expression and the prolongation of infarction time." (PMID 40520774, 2025). "ICV injection of TLR4-SiRNA improves LV dP/dt and LVEDP, not infarct size and LV fractional shortening." (PMID 23874864, 2013).